INS (insulin)
Diseases named in the same sentence as INS in open-access papers (continued):
Sharing a sentence is not in itself a finding about the gene and the disease.
cancer (continued). "The results showed that genes with RNA SNVs in muscles of the BE3 mice revealed enrichment for insulin signaling, lipid metabolism and cancer related pathways." (PMID 36997536, 2023). "Most remarkably, wt-ANXA7 induced tissue-specific alterations in the autophagy-relevant insulin/PI3K/Akt/mTOR signaling cascade (including also FOXO and PTEN) that has a central role in carcinogenesis as one of the most mutated systems in human cancer." (PMID 37240163, 2023). "Fasting affects the living environment of cancer cells by reducing levels of insulin, blood glucose, etc., and improves the clinical outcome of patients with cancer." (PMID 36845049, 2023). "The incidence rate of newly developed cases requiring insulin treatment was 2.34 per 1000 person years in the cancer group and 1.74 per 1000 person years in the comparison group." (PMID 36831436, 2023). "Using D2O probing and SRS (DO-SRS) imaging we then examined the impacts of methionine and insulin on lipid metabolism in cancer cells." (PMID 35359364, 2022). "Considering their complex regulatory role in cell growth and metabolism, the influence of insulin and incretin-based drugs on the cancer profile of diabetic patients has attracted widespread attention." (PMID 35933633, 2022). "Using Ingenuity Pathway Analysis, we observed significant evidence for enrichment for 47 molecular pathways, which included many signalling pathways affecting metabolic health and cancer, and where the top pathway was Insulin Signalling (P = 4 × 10−6)." (PMID 35843982, 2022). "•Improved body metabolism with increased insulin sensitivity and lowered cancer-promoting sex hormones." (PMID 37990728, 2022). "The exosomes carrying let-7a were found to promote a metabolic shift towards enhanced mitochondrial oxidative phosphorylation in macrophages by suppressing insulin-Akt-mTOR signaling to enhance cancer progression." (PMID 36176760, 2022). "First, we are yet to functionally link the CAMKK2-mediated changes in circulating insulin levels to the observed changes in cancer cell size, mTOR signaling, and cancer progression." (PMID 35741020, 2022). "Carbohydrate intake restriction, followed by decreased insulin levels in patients on low-carbohydrate diets such as the KD, can partially suppress these pathways in cancer cells." (PMID 36079756, 2022). "The significantly altered metabolic pathways were cholesterol metabolism, choline metabolism in cancer, fat digestion and absorption, regulation of lipolysis in adipocytes, and insulin resistance." (PMID 36465658, 2022). "One of the first transgenic mouse models of cancer developed was a model of PanNETs, with the rat insulin promoter (RIP) driving transgenic expression of the SV40 large T antigen in β cells." (PMID 35976056, 2022). "Methionine dependence, also known as the Hoffman effect, has been explored in TNBC and other cancers, but fewer studies explored the effects of excess methionine, and fewer still, the tandem manipulation of methionine and insulin." (PMID 35359364, 2022). "In a three-month ketogenic diet study involving 55 cancer patients, it was found that the total ketone body increased significantly, and the levels of fasting blood glucose and insulin decreased significantly." (PMID 36235844, 2022). "The KEGG pathway analysis indicated that the DEGs were enriched in apoptosis, pathways in cancer and insulin signaling pathway." (PMID 36199443, 2022). "Simultaneously, we evaluated the utility of several insulin-sensitizing oral agents with anti-cancer activity that returns MDR cells to treatment-sensitive states." (PMID 36077749, 2022). "Regarding previous or coexisting medication use, both groups of patients with cancer were more likely than controls to be prescribed with diuretics, NSAIDs, metformin, sulfonylureas, and insulin." (PMID 35600378, 2022). "As model proteins relevant to chronic inflammation and cancer, we used gas plasma-treated insulin and CXCL8." (PMID 36366323, 2022).
cancer (continued). "Other experimental strategies to indirectly target insulin signaling in combination with other cancer treatments, such as chemotherapy and immunotherapy, are also being actively pursued in the clinic, and will be discussed later in this review." (PMID 35244142, 2022). "ASB6 acts as an adapter protein which participates in the activation of insulin signaling, however, little is known about its role in cancer." (PMID 36446779, 2022). "Insulin is a crucial growth agent that promotes cancer by boosting cell mitosis and migration while also suppressing apoptosis." (PMID 35145826, 2022). "Over a long period, insulin has been regarded as a compensatory hormone of IGF-1 in cancer development and progression." (PMID 35252207, 2022). "Drug and molecule releasing hydrogels such as insulin-releasing hydrogels and cancer drug-releasing hydrogels can deliver insulin and cancer drugs, respectively, to their desired locations to maximize results and to minimize harmful drug effects." (PMID 35163339, 2022). "Given the impact of metformin on the improvement of insulin sensitivity, evidence indicates that metformin also has a beneficial effect in the prevention and management of cancer." (PMID 36297423, 2022). "Recent clinical data show how multiple dietary changes involving calorie intake reduction or FMDs are able to counteract growth-promoting factors—such as glucose, IGF-1, or insulin—in cancer." (PMID 35681689, 2022). "The insulin resistance and systemic inflammatory cytokines in cancer cachexia patients also impact adipose tissue." (PMID 36072935, 2022). "With rising recognition of the interactions between insulin, substrates, and tumor progression, dietary modifications represent an area of burgeoning interest in cancer therapeutics." (PMID 35244142, 2022). "The insulin group had larger or smaller lesions than the control group, depending on the size of the lesions, and the combination of insulin and chemotherapy was ineffective in the treatment of malignant tumours." (PMID 36776356, 2022). "Insulin signaling maintains glucose homeostasis and is involved in cancer development and progression." (PMID 35565312, 2022). "SHP2 is an important human tyrosine phosphatase with key roles in cancer, immune responses and insulin signaling." (PMID 36114179, 2022). "mTORC2 primarily functions as an effector of the insulin/PI3K signaling and consequently is specifically involved in the development of cancer induced by upregulation of insulin/PI3K signaling." (PMID 35157728, 2022). "Various diets that modulate insulin levels have been proposed as adjunctive therapies to cancer treatment, including calorie restriction, low-carbohydrate and ketogenic diets, and intermittent fasting strategies." (PMID 36079800, 2022). "In cancer patients, the utilization of glucose by tumor cells leads to reduced circulating insulin, thus reducing activation of this pathway." (PMID 35326491, 2022). "Fourthly, the genetic instruments for leptin, adiponectin, and fasting insulin, explained only a small fraction of the genetic variance in these traits, which, might have resulted in low statistical power and missed associations between these traits and certain cancers." (PMID 36558416, 2022). "Further, previous studies have found that physical activity and chronic hyperglycemia (i.e., elevated hemoglobin A1c) are correlated with certain cancer-related biomarkers (e.g., insulin-related pathways and inflammation)." (PMID 36099282, 2022). "Known as the main enzyme responsible for the degradation of insulin, an essential growth factor for healthy cells and cancer cells, IDE has also been shown to behave like a chaperone and interact with the proteasome." (PMID 35406791, 2022). "Individuals with cancer cachexia have higher endogenous glucose production, increased gluconeogenesis and greater insulin resistance." (PMID 35830152, 2022).
cancer (continued). "Studies revealed that insulin has a more substantial effect on the survival of cancer cells, while IGF-1 was better in the cell cycle and proliferation." (PMID 35252207, 2022). "With respect to TNBC, insulin and methionine both independently drive cancer proliferation and affect lipid metabolism, and separate studies indicate insulin metabolism directly affects the uptake of amino acids in yeast and dogs." (PMID 35359364, 2022). "Insulin stimulates local angiogenesis, which is essential to help cancer cells get more oxygen and nutrients from the blood vessels." (PMID 35252207, 2022). "Insulin is also a growth factor: it induces the proliferation and growth of cancer cells, principally via the MAPK pathway." (PMID 35478209, 2022). "KEGG enrichment analysis revealed that the interacting partners of PIK3R3 are involved in the ErbB signaling pathway, proteoglycans in cancer, FoxO, prolactin, chemokine, and insulin signaling pathways." (PMID 35761259, 2022). "Taken together, these results suggest that the insulin-activated CXCL12/CXCR4 axis sustains a paracrine feedforward loop coupling cancer and stromal cells, thus fostering a motile phenotype in BCAHC-1 cells." (PMID 35672854, 2022). "Physical activity plays a protective role in developing cancer with some hormonal regulation mechanisms such as lowering insulin levels." (PMID 36575538, 2022). "Given the role of insulin in the maintenance of skeletal muscle, this evidence supports the involvement of insulin resistance in the development of tissue wasting in cancer cachexia patients." (PMID 35388147, 2022). "KEGG pathway analysis displayed that the dysregulated genes were enriched in focal adhesion, proteoglycans in cancer, central carbon metabolism in cancer, and insulin secretion." (PMID 35310605, 2022). "Some major examples of hydrogel drugs and biomolecule deliveries are the delivery of cancer therapy and the delivery of insulin particles to lower blood sugar levels." (PMID 35163339, 2022). "This lipid adduct can be an agonist of GPR55, a G-protein coupled receptor, whose biological activities include the modulation of immune cells and insulin secretion, and also have a potential mitogen activity in cancer cells." (PMID 36552648, 2022). "The results showed that two human disease pathways, insulin resistance and choline metabolism in cancers, involve most of the differential lipid metabolites." (PMID 35880567, 2022). "Both insulin and leptin have been shown to promote the growth of cancer cells, whilst leptin also functions as an inflammatory cytokine." (PMID 35681688, 2022). "Growing evidence has underlined the importance of acylcarnitines in various physiological processes such as fatty acid oxidation, energy homeostasis, and insulin secretion and sensitivity regulation, and proliferation of cancer cells." (PMID 36232780, 2022). "The highly upregulated PYGM gene, an enzyme involved in glycogenolysis, is involved in diverse insulin and glucagon signaling, necroptosis, inflammatory response, cellular energy support, and cancer progression." (PMID 35741360, 2022). "In combination with other risk factors including inflammatory markers, sex hormones, and elevated glucose levels, insulin appears to confer independent and perhaps synergistic effects on tumor progression and cancer outcomes." (PMID 35244142, 2022). "Insulin has been shown to stimulate cell division, supporting the growth and spread of cancer cells and making them more difficult to eliminate." (PMID 35705722, 2022). "It is evident that the insulin pathway is responsible for developing various human cancers, such as BC." (PMID 36233373, 2022). "Use of insulin-lowering diets can also improve anti-cancer treatment efficacy in preclinical models." (PMID 36079800, 2022). "Insulin-sensitizers have been shown to reduce the incidence of cancer in humans prescribed them, and we previously demonstrated that they also reverse and delay MDR development in vitro." (PMID 36077749, 2022).
cancer (continued). "Decreasing the level of insulin in the blood inhibits the progression of cancer cells, as the higher level of insulin activates a higher number of insulin receptors on cancer cells, leading to the excessive growth of tumor cells." (PMID 36233373, 2022). "Through KEGG analysis, the most significantly enriched pathways for the dysregulated mRNAs in the P. multocida strain serotype A- and D-stimulated groups were pathways involved in cancer and insulin signaling (p-value < 0.05), respectively." (PMID 35321408, 2022). "A recent study of pancreatic ductal adenocarcinoma patients links mammalian IGFBP2 to cachexia, suggesting that the insulin/IGF signaling-related mechanism of cancer cachexia is conserved." (PMID 35319749, 2022). "This means that physical activity can reduce the likelihood of developing cancer by improving insulin sensitivity and glucose metabolism." (PMID 36510257, 2022). "And 21 patients were using oral antidiabetic, 20 patients were using insulin, 88 patients were using antihypertensive, and 7 patients were using various antineoplastic chemotherapeutics due to malignancy." (PMID 35634937, 2022). "Although studies have indicated that glycemic load and its effects on the insulin pathway serve as the primary link between sugar and cancer, there are other potential mechanisms." (PMID 36551528, 2022). "Functional enrichment analysis identified the following pathways: axon development, cognition, cholinergic synapse, insulin signalling, and several types of cancer (highlighted in yellow)." (PMID 36411288, 2022). "Insulin and IGFs participate in the pathogenesis, progression and prognosis of cancer by increasing cancer cell proliferation." (PMID 35406791, 2022). "That insulin has direct cancer-promoting effects on tumour cells has implications for clinical management of obese and diabetic cancer patients." (PMID 34554347, 2022). "After the enrichment of the up-regulated gene pathways, arachidonic acid metabolism, choline metabolism in cancer, retrograde endocannabinoid signaling, and insulin resistance showed significant differences between the groups." (PMID 35056885, 2022). "Previous physical activity interventions showed beneficial changes in biomarkers implicated in these pathways, including insulin, leptin, IGFs, and C-reactive protein (CRP) in cancer survivors." (PMID 36099282, 2022). "The major pathways identified in each group included “cancer”, “regulation of actin cytoskeleton”, “proteoglycans in cancer”, “focal adhesion”, and “insulin signaling pathway”." (PMID 35101056, 2022). "Insulin also enhanced angiogenesis by promoting the expression of vascular endothelial growth factor (VEGF) in cancer cells." (PMID 35252207, 2022). "Beyond acting as a metabolic integrator, insulin coordinates cancer cell metabolism, proliferation and motility through its action on Akt/mTOR axis, lipogenesis and mitochondria." (PMID 36012397, 2022). "In recent years, the roles of lncRNAs in regulating metabolism in cancer, insulin, and chicken have been reported, while, in plants, studies are still limited." (PMID 35678657, 2022). "Laboratory studies revealed that, under an IGF-1 inhibited environment, insulin works as the backup line for cancer cells to gain chemoresistance and resist IGFR related therapies in PDA cells." (PMID 35252207, 2022). "Such exosomes exhibit pro-cancer stem-cell-like cell formation and pro-invasive and pro-metastatic behaviors in breast cancer cell models compared with insulin-sensitive adipocytes or adipocytes isolated from adipose tissue of non-diabetic subjects." (PMID 36291860, 2022). "Similar to insulin, incretin-based drugs also exhibit very interesting contradictions and inconsistencies in response to different cancer phenotypes, including BTC." (PMID 35933633, 2022). "Some examples of hydrogels used for drug and biomolecule delivery include insulin encapsulated hydrogels and hydrogels that encompass cancer drugs for desired controlled release." (PMID 35163339, 2022).
cancer (continued). "Overexpression or loss of Cdc42 also contributes to the development of some benign diseases through the same or similar signaling pathways as malignant tumors, such as insulin secretion, insulin resistance, airway inflammation and neurodegenerative diseases." (PMID 35154449, 2022). "KEGG pathway analysis displayed that the dysregulated genes in specimens with high RIPK4 expressions were enriched in focal adhesion, proteoglycans in cancer, central carbon metabolism in cancer, and insulin secretion." (PMID 35310605, 2022). "PKCθ has been suggested to be involved in other biological processes, such as platelet activation, insulin response, or cancer progression." (PMID 35216371, 2022). "In a pilot study of 10 patients with advanced cancers who consumed insulin-lowering diets defined as dietary carbohydrate restriction to 5% of total caloric intake, mean caloric intake decreased by 35% and weight decreased by a median of 4%." (PMID 36079800, 2022). "CAMKK2-regulated differences in cancer cell size and mTOR signaling (assessed by p-S6 IHC) combined with the sustained alterations in circulating insulin levels suggest that insulin mediates CAMKK2’s effects on cancer via control of systemic metabolism." (PMID 35741020, 2022). "PPARγ is highly expressed in adipose tissue (AT), however the effects of pioglitazone to improve insulin sensitivity are also evident in other tissues and PPARγ agonism has been shown to alter cancer derived extracellular vesicle (EV)-miRNAs." (PMID 36120427, 2022). "When relevant, the roles of IGF1 and IGF2 in cancer biology will be compared to those of the closely related insulin molecule." (PMID 36479090, 2022). "In cancer cachexia, insulin plays an important role in communications between the pancreas and liver and between the pancreas and tumors." (PMID 36105371, 2022). "On the other hand, AMPK can inhibit DNA demethylation of the SREBP-1 promoter mediated by TDG, suggesting that TDG regulated by insulin or metformin is a potential therapeutic target for T2DM-related cancers." (PMID 35912181, 2022). "This gene’s activity is normally regulated by insulin and nutritional status; however, this regulation is lost throughout the cancer process." (PMID 35399507, 2022). "In pancreatic islets of Langerhans isolated from carcinoma-bearing rats, insulin secretion is decreased in response to glucose stimulation, indicating impaired insulin sensitivity." (PMID 35388147, 2022). "Mechanistically, increasing evidence demonstrated that the anti-cancer activity of metformin can be exerted by an insulin-independent or direct mechanism, and an insulin dependent one." (PMID 35008275, 2021). "The growth hormone/insulin growth factor-1 (GH/IGF-1)/ insulin pathway and its downstream effectors, in fact, are known to promote aging and/or age-related diseases, including cancer, in many model organisms." (PMID 34572814, 2021). "KEGG analysis revealed that the genes coexpressed with Rac3 were mainly enriched in the cell cycle, pathways in cancer, Ras signaling and insulin signaling pathways." (PMID 34257551, 2021). "In cachectic cancer patients, it was reported recently that serum insulin level is significantly reduced." (PMID 34212132, 2021). "Ceramides function as either intra- or intercellular messengers and as regulatory molecules and play roles in signal transduction, inflammation, angiogenesis, insulin resistance, neurodegeneration, and cancer/cancer therapy." (PMID 34065331, 2021). "Apart from the previously highlighted mechanisms, glucose increases insulin and insulin-like growth factors which can further function as cancer promoters." (PMID 34422883, 2021). "Thiscould suggest a new mechanism for the role of miR-221 in cancer drugs resistance induced by insulin." (PMID 34308576, 2021).